LY6G6F (lymphocyte antigen 6 family member G6F)
Description:
May play a role in the downstream signal transduction pathways involving GRB2 and GRB7.
Synonyms: C6orf21; G6F; LY6G6D; NG32; LY6G6
Tractability: Antibody: UniProt places it where antibodies can reach, with high confidence; its Gene Ontology location is reachable by antibodies, with high confidence; UniProt predicts a signal peptide or a membrane-spanning region.
Gene: Protein-coding gene on chromosome 6 (31,706,866 to 31,710,679, forward strand). Ensembl gene ENSG00000204424.
Subcellular location: Cell membrane
Pathways (Reactome):
Hemostasis: Platelet degranulation
Gene Ontology:
Molecular function: protein binding
Cellular component: plasma membrane; platelet alpha granule membrane
Genetic constraint (gnomAD): Loss-of-function variants: 26 observed, 34.73 expected, observed/expected ratio (o/e) 0.75, 90% interval 0.55 to 1.04. The upper end of that interval is the gene's LOEUF score, 1.04, which puts it in group 4 of 6, group 1 being the genes least tolerant of losing a copy. Missense variants: 317 observed, 392.59 expected, observed/expected ratio (o/e) 0.81, 90% interval 0.74 to 0.89. Synonymous variants: 132 observed, 156.66 expected, observed/expected ratio (o/e) 0.84, 90% interval 0.73 to 0.97.
Homologues: Orthologues: dog LY6G6F (82% identical), pig LY6G6F (76% identical), guinea pig LY6G6F (69% identical), mouse Ly6g6f (66% identical). Paralogues in human: LY6G6D (5% identical).